UFC1 (ubiquitin-fold modifier conjugating enzyme 1)
Description:
E2-like enzyme which specifically catalyzes the second step in ufmylation. Accepts the ubiquitin-like modifier UFM1 from the E1 enzyme UBA5 and forms an intermediate with UFM1 via a thioester linkage. Ufmylation is involved in various processes, such as ribosome recycling, response to DNA damage, interferon response or reticulophagy (also called ER-phagy).
Synonyms: HSPC155; NEDSG
Tractability: Small molecule: it has a high-quality binding pocket. PROTAC: UniProt records ubiquitination sites on it; ubiquitination databases record sites on it; its protein half-life has been measured.
Gene: Protein-coding gene on chromosome 1 (161,152,776 to 161,158,856, forward strand). Ensembl gene ENSG00000143222.
Subcellular location (Human Protein Atlas): Nuclear speckles; Cytosol
Gene Ontology:
Molecular function: protein binding; UFM1 conjugating enzyme activity; UFM1 transferase activity
Biological process: brain development; protein K69-linked ufmylation; protein ufmylation; response to endoplasmic reticulum stress; reticulophagy; regulation of type II interferon production
Cellular component: extracellular exosome; cytoplasm
Genetic constraint (gnomAD): Loss-of-function variants: 22 observed, 30.05 expected, observed/expected ratio (o/e) 0.73, 90% interval 0.52 to 1.05. The upper end of that interval is the gene's LOEUF score, 1.05, which puts it in group 4 of 6, group 1 being the genes least tolerant of losing a copy. Missense variants: 189 observed, 220.21 expected, observed/expected ratio (o/e) 0.86, 90% interval 0.76 to 0.97. Synonymous variants: 61 observed, 79.71 expected, observed/expected ratio (o/e) 0.77, 90% interval 0.62 to 0.95.
Homologues: Orthologues: macaque UFC1 (100% identical), pig UFC1 (100% identical), chimpanzee UFC1 (99% identical), guinea pig UFC1 (99% identical), dog UFC1 (99% identical), rabbit UFC1 (98% identical), rat Ufc1 (98% identical), mouse Ufc1 (97% identical), tropical clawed frog ufc1 (87% identical), zebrafish ufc1 (86% identical), Drosophila melanogaster Ufc1 (78% identical), Caenorhabditis elegans ufc-1 (69% identical).
Diseases named in the same sentence as UFC1 in open-access papers:
UFC1 is named in the same sentence as 43 diseases in open-access papers, as found by Europe PMC text mining. Sharing a sentence is not in itself a finding about the gene and the disease. The quoted sentences say what the papers report.
non-small cell lung carcinoma (10 papers, 2020 to 2025). A group of at least three distinct histological types of lung cancer, including non-small cell squamous cell carcinoma, adenocarcinoma, and large cell carcinoma. "Furthermore, exosome-delivered long non-coding RNA (lncRNA) UFC1 has been implicated in promoting non-small cell lung cancer progression through EZH2-mediated epigenetic silencing of PTEN expression." (PMID 38528957, 2024). "Exosome-borne UFC1, derived from non-small cell lung cancer cells, promotes the proliferation, migration, and invasion of these cells through UFC1-mediated metastasis." (PMID 38528957, 2024). "This suggests the key role of exosomes in facilitating the transfer of UFC1 to non-small cell lung cancer cells." (PMID 35236381, 2022). "UFC1 is upregulated in lung cancer tissues, serum, and serum exosomes of patients with non-small cell lung cancer and is suggested to mediate their proliferation and invasion." (PMID 35236381, 2022). "Long non-coding RNA (lncRNA) such as ANRIL and UFC1 have been verified as oncogenic genes in non-small cell lung cancer (NSCLC)." (PMID 35327612, 2022). "For example, the expression levels of long non-coding RNA UFC1 were increased in the serum exosomes of non-small cell lung cancer (NSCLC) patients compared to pneumonia patients and healthy controls, with high diagnostic sensitivity and specificity." (PMID 34367259, 2021). "LncRNA UFC1 was upregulated in non-small cell lung cancer (NSCLC) tissues, serum exosomes, and serum, which promoted NSCLC by decreasing phosphatase and tensin homolog deleted on chromosome ten (PTEN) expression." (PMID 34900675, 2021). "Similarly, in non-small cell lung cancer, exosomal lncRNA UFC1 promotes cancer progression and is highly expressed in exosomes derived from NSCLC cells and patient serum, underscoring its role as a diagnostic and prognostic marker." (PMID 40781643, 2025). "Several exosomal lncRNAs and proteins have been identified that originate from non-small cells lung cancer (NSCLC), some of which have a role in neoangiogenesis, e.g., lncRNA-p21 and Ubiquitin-fold modifier conjugating enzyme 1 (UFC1) protein." (PMID 37108672, 2023). "Migration of tumor cells was facilitated by the exosome-mediated transfer of αvβ6 in prostate cancer; miR-21 in bladder cancer; TAM derived exosomes in gastric cancer (GC) cells; and lncRNA ubiquitin-fold modifier conjugating enzyme 1 (UFC1) in non-small cell lung carcinoma (NSCLC)." (PMID 33477340, 2021). "The lncRNA UFC1, transmitted via exosomes, possibly binds to EZH2 to inhibit PTEN levels and stimulate the PI3K/Akt signaling pathway, hence promoting the tumorigenesis of non-small cell lung cancer (NSCLC)." (PMID 36338993, 2022).
hepatocellular carcinoma (8 papers, 2016 to 2026). A malignant tumor that arises from hepatocytes. "Another lncRNA that is associated with HCC cell proliferation is lncRNA UFC1 (Ubiquitin-Fold Modifier Conjugating Enzyme 1), which is a target gene of miR-34a and can promote hepatoma cell proliferation, induce cell cycle, and inhibit cell apoptosis." (PMID 38334963, 2024). "Additionally, the long intergenic noncoding RNA UFC1 interacted directly with HuR to increase β-catenin expression, leading to proliferation enhancement and apoptosis suppression in hepatocellular carcinoma cells (HCC) cells, and intensified growth of xenograft tumors in mice." (PMID 28968471, 2017). "UFC1 was first identified in hepatocellular carcinoma (HCC) as a target of miRNA-34a." (PMID 29970131, 2018). "This study investigated the clinical significance and predictive value of two biologically antagonistic lncRNAs, UFC1 and PTENP1, as circulating biomarkers for hepatocellular carcinoma (HCC) in an Egyptian cohort." (PMID 42042020, 2026).
microcephaly (6 papers, 2018 to 2025). A congenital or acquired developmental disorder in which the circumference of the head is smaller than normal for the person's age and sex. "Mutations in UFM1, as well as in its specific E1 enzyme UBA5 and E2 enzyme UFC1, have been genetically linked to microcephaly." (PMID 39085203, 2024). "Biallelic mutations of UFM1 or UFC1 are also associated with microcephaly, global developmental delay, and seizures." (PMID 36543799, 2022). "The clinical phenotype of previously reported patients with UBA5 and UFM1 mutations are similar to our UFM1 and UFC1 patients, particularly regarding failure to thrive, short stature, microcephaly, GDD, seizures, basal ganglia abnormality, delayed CNS myelination, and cerebellar hypoplasia." (PMID 29868776, 2018). "Moreover, mutations in UFM1 and UFC1 were shown to cause neurologic disease with global developmental delay, progressive microcephaly, short stature and refractory epilepsy, a phenotype highly reminiscent of that observed in individuals with UBA5-related epileptic encephalopathy." (PMID 38046095, 2023). "In a Drosophila model, the disruption of genes in the UFM1 cascade, including UFC1, greatly decreases the number of neuroblasts, resulting in the smaller brain size observed in microcephaly." (PMID 39846712, 2025).
gastric cancer (5 papers, 2018 to 2024). A primary or metastatic malignant neoplasm involving the stomach. "On the contrary, a positive association between the expression level of UFC1 and that of Lin28b was observed in gastric cancer tissues (r = 0.604, P < 0.001)." (PMID 29970131, 2018). "UFC1 expression was negatively associated with that of miR-498 in gastric cancer." (PMID 29970131, 2018). "We reported that UFC1 was upregulated in gastric cancer and UFC1 promoted GC progression by acting as a miR-498 sponge to activate Lin28b expression." (PMID 32242003, 2020). "We have previously shown that UFC1 promotes gastric cancer progression by acting as a ceRNA for miR-498." (PMID 32242003, 2020). "The results of cell counting assay showed that UFC1 knockdown inhibited gastric cancer cell proliferation, which was further confirmed by the results of colony formation assays." (PMID 29970131, 2018). "Our findings not only suggest a critical role of UFC1 in gastric cancer progression but also provide a novel biomarker for gastric cancer diagnosis and therapy." (PMID 29970131, 2018). "UFC1 knockdown also retarded gastric cancer growth in vivo, indicating that UFC1 is critical for gastric carcinogenesis." (PMID 29970131, 2018). "UFC1 knockdown induced cell cycle arrest and cell apoptosis, leading to the inhibition of gastric cancer cell proliferation." (PMID 29970131, 2018). "On the contrary, Lin28b knockdown reversed the promoting role of UFC1 in gastric cancer progression, suggesting that the upregulation of Lin28b contributes, at least in part, to the oncogenic role of UFC1 in gastric cancer." (PMID 29970131, 2018). "UFC1 exerted its oncogenic activities in gastric cancer by sponging miR-498 and derepressing its downstream target Lin28b." (PMID 29970131, 2018). "We demonstrated that UFC1 knockdown inhibited while UFC1 overexpression promoted gastric cancer cell proliferation, migration, and invasion." (PMID 29970131, 2018). "Taken together, these findings suggest that UFC1 function as a miR-498 sponge in gastric cancer cells." (PMID 29970131, 2018). "The identification of UFC1/miR-498/Lin28b signaling axis thus adds new evidence to the important roles of lncRNAs in gastric cancer progression and provides new targets for gastric cancer diagnosis, prognosis and therapy." (PMID 29970131, 2018). "UFC1 knockdown inhibited while UFC1 overexpression promoted gastric cancer cell proliferation, migration and invasion." (PMID 29970131, 2018). "UFC1 promoted gastric cancer cell proliferation, migration and invasion by favoring cell cycle progression, inhibiting cell apoptosis and inducing EMT." (PMID 29970131, 2018). "Moreover, UFC1 overexpression antagonized the suppressive role of miR-498 in gastric cancer cell proliferation, migration and invasion." (PMID 29970131, 2018). "Furthermore, the patients who had high levels of UFC1 came out with a notably poorer prognosis than those who had low levels of UFC1 (P < 0.05).We next examined the expression level of UFC1 in the serum of patients with gastric cancer." (PMID 29970131, 2018). "We identified an increased expression of UFC1 in the serum of gastric cancer patients, which suggests that UFC1 may serve as a potential marker for monitoring progression and prognosis of GC." (PMID 29970131, 2018). "Previous study showed that UFC1 was elevated and predicted poor prognosis of gastric cancer (GC), and knockdown of UFC1 inhibited the proliferation, migration, and invasion of GC cells." (PMID 35586092, 2022). "However, the expression, clinical value, and biological roles of UFC1 in gastric cancer remain unclear." (PMID 29970131, 2018). "Moreover, UFC1 was present in the serum exosomes of gastric cancer patients." (PMID 29970131, 2018). "However, UFC1 co-transfection reversed the suppressive roles of miR-498 in GC cell proliferation, migration and invasion.Taken together, these findings suggest that miR-498 plays a tumor suppressive role in gastric cancer." (PMID 29970131, 2018).
gastric cancer (continued). "In addition, UFC1 knockdown reversed EMT phenotype of GC cells and inhibited their migration and invasion, suggesting a key role of UFC1 in gastric cancer metastasis." (PMID 29970131, 2018). "The high level of exosomal UFC1 could distinguish gastric cancer patients from healthy controls, indicating an important value of serum exosomal UFC1 in GC diagnosis." (PMID 29970131, 2018). "We first detected the relative expression levels of UFC1 in 79 paired gastric cancer tissues and adjacent non-tumor tissues." (PMID 29970131, 2018).
colorectal cancer (4 papers, 2016 to 2022). A primary or metastatic malignant neoplasm that affects the colon or rectum. "Knockdown of UFC1 suppresses colorectal cancer cell proliferation and induces apoptosis though the activation of p38 signaling pathway." (PMID 29970131, 2018).
Encephalopathy (3 papers, 2018 to 2023). Encephalopathy is a term that means brain disease, damage, or malfunction. "Mutations within the TAK motif (T106I and K108A) impair UFC1 function and are associated with human diseases, such as encephalopathy." (PMID 37947621, 2023). "Meantime, biallelic UFC1 variants disrupting UFM1-UFC1 formation have been identified in children with severe early-onset encephalopathy, also arguing for an essential role for UFMylation in brain development." (PMID 36743909, 2022). "In addition, two biallelic UFC1 mutations (T106I and R23Q) and one biallelic UFM1 mutation (R81C), which impaired UFM1-UFC1 intermediate formation and resulted in a widespread reduction in cellular UFMylation, were identified in patients with severe early-onset encephalopathy." (PMID 37947621, 2023).
lung carcinoma (3 papers, 2020 to 2024). "We collected 66 pairs of human lung cancer tissues and their adjacent normal tissues to evaluate the expression levels of UFC1 by qRT-PCR." (PMID 32242003, 2020). "For instance, lncRNA UFC1 is suggested to promote lung cancer progression." (PMID 35236381, 2022).
cervical cancer (2 papers, 2020 to 2022). A primary or metastatic malignant neoplasm involving the cervix. "In cervical cancer, UFC1 upregulated FOXP3 expression through competitively binding miR-34a, promoting cervical cancer growth and metastasis." (PMID 32242003, 2020).
lymph node metastasis (2 papers, 2021 to 2023). "UFC1 expression was related to lymph node metastasis, distant metastasis, and clinical stage." (PMID 37189687, 2023). "Moreover, the serum UFC1 level was correlated with lymph node metastasis, distant metastasis, and clinical stage." (PMID 34439315, 2021).
mild cognitive impairment (2 papers, 2024). "Elevated UFC1 levels in the CSF of individuals with mild cognitive impairment in sporadic AD suggest its involvement in AD’s pathogenesis 75,76." (PMID 39108475, 2024). "Candidate genes with higher area under the receiver operating characteristic curve values were screened, and the expression trend of Ubiquitin-Fold Modifier Conjugating Enzyme 1 (UFC1) gradually decreased from healthy controls to mild cognitive impairment and then to AD." (PMID 39610716, 2024).
osteoarthritis (2 papers, 2019 to 2021). A noninflammatory degenerative joint disease occurring chiefly in older persons, characterized by degeneration of the articular cartilage, hypertrophy of bone at the margins and changes in the synovial membrane. "In contrast, lncRNA UFC1 was downregulated in osteoarthritis, and the upregulation of lncRNA UFC1 promotes the proliferation of chondrocyte." (PMID 31387631, 2019).
pancreatic cancer (2 papers, 2021). "For instance, UFC1 not only serves as a diagnostic marker but also facilitates the prediction of the prognosis of pancreatic cancer." (PMID 34827663, 2021). "Compared to healthy subjects, the level of serum UFC1 in pancreatic cancer patients was significantly higher." (PMID 34439315, 2021). "Multivariate analyses have also shown the potential of UFC1 expression levels as an independent prognostic factor for pancreatic cancer." (PMID 34827663, 2021). "Moreover, serum levels of UFC1 expression are relatively higher in patients with pancreatic cancer compared with healthy controls." (PMID 34827663, 2021). "ROC analysis showed that serum UFC1 levels could effectively distinguish patients with pancreatic cancer from healthy subjects." (PMID 34439315, 2021). "The role of serum UFC1 in the diagnosis of pancreatic cancer was investigated." (PMID 34439315, 2021).
pneumonia (2 papers, 2020 to 2021). An acute, acute and chronic, or chronic inflammation focally or diffusely affecting the lung parenchyma, caused by an infection in one or both of the lungs (by bacteria, viruses, fungi, or mycoplasma.). "The expression level of exosomal UFC1 was also increased in NSCLC patients compared to pneumonia patients and healthy donors." (PMID 32242003, 2020). "UFC1 expression was also upregulated in the serum of NSCLC patients compared to that of pneumonia patients and healthy donors." (PMID 32242003, 2020). "We reported that UFC1 was highly expressed in serum and serum exosomes of NSCLC patients compared to that of pneumonia patients and healthy controls, indicating that UFC1 may represent a convenient and reliable biomarker for the diagnosis of NSCLC patients." (PMID 32242003, 2020).
Becker muscular dystrophy (1 paper, 2022). Becker muscular dystrophy (BMD) is a neuromuscular disease characterized by progressive muscle wasting and weakness due to degeneration of skeletal, smooth and cardiac muscle. "Furthermore, the expression of UFC1 is also up-regulated in skeletal myocytes differentiated from induced pluripotent stem cells derived from familial ALS (C9ORF72 mutations), and the expression of UBA5, the E1 ligase for UFMylation has recently been associated with Becker muscular dystrophy." (PMID 36472367, 2022).
diffuse large B-cell lymphoma (1 paper, 2016). "However, despite the amplification of UFC1 in pancreatic adenocarcinoma and amplification of both UFC1 and UFL1 in diffuse large B-cell lymphoma, high percentage of UFL1 deletion and UFL1/UFM1 deletion was also detected in pancreatic adenocarcinoma and diffuse large B-cell lymphoma, respectively." (PMID 27212118, 2016).
gastritis (1 paper, 2018). Inflammation of the stomach. "The serum levels of UFC1 were elevated in GC patients compared to that in gastritis patients and healthy controls (P < 0.001)." (PMID 29970131, 2018).
Infantile encephalopathy (1 paper, 2018). Encephalopathy with onset in the infantile period. "Similar to our previous work on UBA5-related severe infantile encephalopathy, we show that mutations in UFM1 itself as well as in UFC1, encoding the sole E2 conjugating enzyme for UFM lead to widespread impairment of ufmylation." (PMID 29868776, 2018).
liver cancer (1 paper, 2026). An epithelial or non-epithelial malignant neoplasm that arises from the liver. "UFC1 expression was increased progressively with advancing fibrosis grade and Barcelona Clinic Liver Cancer (BCLC) stage, while PTENP1 levels diminished with BCLC stage." (PMID 42042020, 2026).
liver disease (1 paper, 2019). "In summary, our results suggest that UFC1 (4′,′5-(Methylenedioxy)-2-nitrocinnamic acid) may interact directly with Z-hAAT and render the protein susceptible to degradation mechanisms within cells in a manner beneficial for AATD associated liver disease." (PMID 31817705, 2019).
Liver fibrosis (1 paper, 2019). "Liver fibrosis, measured by picrosirius red stain and collagen III protein levels were reduced after three months of UFC1 treatment." (PMID 31817705, 2019).
neuroblastoma (1 paper, 2016). Neuroblastoma (NB) is the most common solid, extracranial childhood tumor. "NCAM140, an isoform of NCAM, was shown to interact with UFC1 through its cytoplasmic domain and co-localize with UFC1 on the surface of B35 neuroblastoma cells." (PMID 27212118, 2016).
Obesity (1 paper, 2024). Accumulation of substantial excess body fat. "As expected, the expression levels of hepatic Uba5, Ufc1, Ufl1, and Ufm1 are significantly reduced in patients with obesity, MASLD, and MASH by analyzing the public data sets." (PMID 39858578, 2024).
Spasticity (1 paper, 2023). A motor disorder characterized by a velocity-dependent increase in tonic stretch reflexes with increased muscle tone, exaggerated (hyperexcitable) tendon reflexes. "Variants in UFC1 (OMIM: #610554) cause a neurodevelopmental disorder with spasticity and poor growth (NEDSG, OMIM: #618076)." (PMID 38079206, 2023).